AKAP4 (A-kinase anchoring protein 4)
Diseases named in the same sentence as AKAP4 in open-access papers (continued):
Sharing a sentence is not in itself a finding about the gene and the disease.
ovarian carcinoma (4 papers, 2017 to 2024). A malignant neoplasm originating from the surface ovarian epithelium. "Kumar claimed that the growth and survival of ovarian cancer cells were induced by AKAP4 through the regulation of c-AMP/PKA signaling." (PMID 35253625, 2022). "Further, PKA inhibitor (H89) and oxidative stress resulted in similar phenotype of ovarian cancer cells as observed in AKAP4 ablated cells." (PMID 28881798, 2017). "Effect of ablation of AKAP4 on tumor growth in SCID mice ovarian cancer xenograft model was evaluated." (PMID 28881798, 2017). "This is line with our data wherein, phenotypically AKAP4 depleted ovarian cancer cells had reduced invasive properties." (PMID 28881798, 2017). "Our results showed that ablation of AKAP4 resulted in increased reactive oxygen species (ROS) generation, DNA damage, cell cycle arrest and apoptosis in ovarian cancer cells." (PMID 28881798, 2017). "By gene silencing approach, ablation of AKAP4 in ovarian cancer cells provoked cell cycle arrest with decreased expression of key molecules involved in the various events of cell cycle and reduced tumor growth." (PMID 28881798, 2017). "Further, we also investigated the effect of ablation of AKAP4 on tumor growth in SCID mice ovarian cancer xenograft mouse model." (PMID 28881798, 2017). "AKAP4 gene expression was examined by RT-PCR which showed presence of AKAP4 gene expression in all three ovarian cancer cells." (PMID 28881798, 2017). "PKA inhibitor (H89) and oxidative stress (H2O2 treatment) resulted in similar phenotype of ovarian cancer cells as observed in AKAP4 ablated cells." (PMID 28881798, 2017). "In present study we investigated the role of AKAP4 in various malignant properties in ovarian cancer cells in vitro and in in vivo ovarian cancer xenograft mouse model." (PMID 28881798, 2017). "Clearly, our study shows that AKAP4 ablation lead to compromised survival of ovarian cancer cells through inhibition of various pro- survival signals." (PMID 28881798, 2017). "Similarly, TEX19, SPAG9, HSP70‐2, and AKAP4 can promote the invasion and metastasis of ovarian cancer, and the downregulation of these genes can significantly inhibit the migration and invasion ability of ovarian cancer cells." (PMID 38896069, 2024). "Furthermore, AKAP4 knockdown inhibits wound healing and reduces metastatic markers in ovarian cancer cells." (PMID 30609934, 2019). "Interestingly, our study in AKAP4 ablated ovarian cancer cells showed decreased expression of p-CREB, β-catenin, PCNA, cyclinA2, cyclinB1, cyclinD1, cyclinE along with their CDK partners which has important role in cellular proliferation." (PMID 28881798, 2017). "Intrigued by decreased expression of PKA due to AKAP4 knockdown, we further examined whether pharmacological inhibition of PKA could mimic AKAP4 ablated phenotype in ovarian cancer cells." (PMID 28881798, 2017). "Therefore, in the present study, employing gene silencing approach, we investigated the effect of ablation of AKAP4 in ovarian cancer cells which showed decreased expression of PKA and CREB." (PMID 28881798, 2017). "Ablation of CREB in ovarian cancer cells (A10 and Caov-3) mimicked AKAP4 ablated phenotype." (PMID 28881798, 2017). "Our data suggests that AKAP4 may play an important role for ovarian cancer cell survival, and it may be targeted as a novel therapeutic intervention in ovarian cancer." (PMID 28881798, 2017). "Thus, AKAP4 may be a potential novel therapeutic target in ovarian cancer and warrants further studies." (PMID 28881798, 2017). "In conclusion our study suggested that AKAP4 might be playing role in ovarian cancer growth." (PMID 28881798, 2017). "Also, AKAP4 depletion in ovarian cancer cells revealed reduced tumor growth in vivo." (PMID 28881798, 2017). "Collectively, for the first time our data showed the involvement of AKAP4 in PKA degradation and perturbed signaling through PKA-CREB axis in AKAP4 ablated ovarian cancer cells." (PMID 28881798, 2017).
ovarian carcinoma (continued). "Gene silencing approach revealed that various oncogenic properties of ovarian cancer cells including cell cycle regulation, apoptosis and EMT were downregulated in AKAP4 depleted cells." (PMID 28881798, 2017). "Moreover, separate studies in ovarian cancer demonstrated that the expression rates of Sp17 (CT22), SSX (CT5), AKAP3 (CT82), AKAP4 (CT99), and PLAC1 (CT92) were 43%, 26%, 58%, 89%, and 21%, respectively." (PMID 38896069, 2024). "Although AKAP4 mRNA and protein were not expressed in 21 matched adjacent non-cancerous tissues, they were detected in 89% (34/38) of ovarian carcinoma tissues." (PMID 30609934, 2019). "Some of the AKAPs considered to be CT genes in ovarian cancer include AKAP3 and AKAP4." (PMID 30609934, 2019). "However, the putative function and involvement of AKAP4 in various signaling modules and in PKA-CREB signaling has not been studied in ovarian cancer cells so far." (PMID 28881798, 2017).
asthenozoospermia (3 papers, 2021 to 2025). "Mutations in FSIP2, characterized by the absence of CPC, IDA, and ODA, can cause idiopathic asthenozoospermia due to the lack of AKAP4 protein." (PMID 40469444, 2025). "Thus, idiopathic asthenozoospermia can be monitored through AKAP3, AKAP4, and FSIP2 within the cAMP/PKA signaling pathway." (PMID 40469444, 2025).
colorectal cancer (3 papers, 2015 to 2022). A primary or metastatic malignant neoplasm that affects the colon or rectum. "For instance, evaluated AKAP4 expression is found in multiple tumors, and high AKAP4 expression positively impacts cell proliferation, migration, and invasion abilities in several cancers, including cervical cancer, colorectal cancer, and ESCC." (PMID 35189899, 2022). "Jagadish reported that AKAP4 promoted the development and progression of colorectal cancer by regulating EMT." (PMID 35253625, 2022). "To further validate our observations on malignant properties of colorectal cancer, following AKAP4 gene silencing, we investigated the role of AKAP4 in in-vivo colorectal xenograft mouse model." (PMID 26590805, 2015). "In the present study, we found that EMT progression in H460 cells and xenograft tumor tissues was significantly suppressed by the knockdown of AKAP4, indicating a positive regulatory effect of AKAP4 on EMT progression, which was consistent with the report described in colorectal cancer." (PMID 35253625, 2022).
lung carcinoma (3 papers, 2015 to 2022). "Several CTAs, such as XAGE, SPAG9 and AKAP4, have been considered as biomarkers for the diagnosis and prognostic prediction of lung cancer." (PMID 35574342, 2022). "AKAP4 is a highly accurate biomarker for the detection of early stage lung cancer." (PMID 26160834, 2015). "AKAP4 expression increases significantly with the advancement of the tumour stage and is independent of age, gender, smoking history or cancer subtype, suggesting that AKAP4 is a highly accurate biomarker for the detection of early-stage lung cancer and prediction of lung cancer progression." (PMID 35574342, 2022). "Our results provide proof of principle that the CTAs SP17/AKAP4/PTTG1 are expressed in both human NSCLC cell lines and primary tumors and can elicit an immunogenic response in lung cancer patients." (PMID 25739119, 2015).
myeloma (3 papers, 2011 to 2022). "HLA-A*0201-restricted cytotoxic T lymphocytes (CTLs) induced by dendritic cells (DCs) transduced with an adenovirus vector encoding the full-length AKAP4 gene were demonstrated to lyse AKAP4+ myeloma cells." (PMID 35967402, 2022). "After confirming the expression of AKAP4 in the primary myeloma cells, we further explored the antigenicity of AKAP4." (PMID 35967402, 2022). "CTLs induced by this peptide can effectively kill HLA-A*0201+AKAP4+ myeloma cell line in vitro and in vivo." (PMID 35967402, 2022). "AKAP4 has high expression in MM cell lines and primary myeloma cells, but low expression in normal tissues." (PMID 35967402, 2022). "In summary, our study confirmed the high expression of AKAP4 in cytoplasm and low expression on cell surface in both primary myeloma cells and myeloma cell lines." (PMID 35967402, 2022). "Our study confirmed the expression of AKAP4 both in the cytoplasm and on the cell surface of myeloma cell lines and human primary myeloma cells." (PMID 35967402, 2022). "Our study confirmed the high expression of AKAP4 in cytoplasm and low expression on cell surface in both primary myeloma cells and myeloma cell lines." (PMID 35967402, 2022). "Finally, the VLMLIQKLL-specific CTLs can lyse the HLA-A*0201+AKAP4+ myeloma cell line U266 in vitro, and inhibit tumor growth in the mice bearing U266 tumors in vivo." (PMID 35967402, 2022). "We examined the expression of AKAP4 by flow cytometry in common myeloma cell lines, including U266 and RPMI-8226, control cell lines THP-1 and RAMOS, and primary myeloma cells." (PMID 35967402, 2022). "AKAP4 630–638 (VLMLIQKLL), which showed the strongest immunogenicity, could induce specific CTLs that showed significant anti-myeloma activity both in vitro and in vivo." (PMID 35967402, 2022). "Its expression and localization in myeloma cells had been confirmed, but accurate function of AKAP4 in the pathogenesis of MM has not been elucidated yet." (PMID 35967402, 2022). "However, we noticed that CTL against AKAP4 is almost absent in the patients, despite the high expression of AKAP4 in the primary myeloma cells." (PMID 35967402, 2022).
Azoospermia (1 paper, 2024). Absence of any measurable level of sperm,whereby spermatozoa cannot be observed even after centrifugation of the semen pellet. "The expression levels of germ-cell-specific mRNAs such as protamine 1 (PRM1), protamine 2 (PRM2), deleted in azoospermia (DAZ), and A-kinase anchoring protein 4 (AKAP4) have also been associated with SRR outcomes, with detectable levels linked to higher SRR rates in some studies." (PMID 39767586, 2024).
colon cancer (1 paper, 2015). "We further assessed AKAP4 mRNA expression in normal colon epithelial cells, CaCo-2, COLO 205, COLO320DM, HCT-15, HT-29, SW480 and SW620 colon cancer cell lines by quantitative PCR (qPCR)." (PMID 26590805, 2015). "Our studies showed that AKAP4 gene and protein expression was expressed in all colon cancer cells while no expression was detectable in normal colon cells." (PMID 26590805, 2015).
cryptorchidism (1 paper, 2023). The failure of one or both testes of a male fetus to descend from the abdomen into the scrotum during the late part of pregnancy. "According to the extent of difference between cryptorchidism and normal testis, the expression of seven downregulated genes (PLCZ1, AKAP4, AKAP3, IZUMO1, SPAG6, CAPZA3, and ROPN1L) were further selected for validation by qPCR." (PMID 38027210, 2023).
varicocele (1 paper, 2015). A condition characterized by the dilated tortuous veins of the spermatic cord with a marked left-sided predominance. "Some of the more abundant proteins in the unilateral varicocele group were lactotransferrin isoform 1 precursor (LTF), fibronectin isoform 3 preprotein (FN1), semenogelin-2 precursor (SEMG2), A-kinase anchor protein 4 isoform 2 (AKAP4), and semenogelin-1 preprotein (SEMG1)." (PMID 25890347, 2015).
tumor (20 papers, 2011 to 2024). "Our prior study investigating AKAP-4 expression in MM and in normal tissues demonstrated that it is a novel MM tumor-associated antigen." (PMID 21765917, 2011). "In vivo xenograft experiments revealed that tumor growth was inhibited by the knockdown of AKAP4, accompanied by the activation of c-AMP/PKA signaling and inhibition of epithelial-mesenchymal transition progression." (PMID 35253625, 2022). "Given that CTAs are usually expressed in normal testicular tissue, the “on-target, off-tumor” effect should be considered when planning immunotherapy against AKAP4." (PMID 35967402, 2022). "Yet another study showed that ablation of AKAP4 resulted in reduced tumor growth in esophageal cancer xenograft mice model." (PMID 28881798, 2017). "Recently, in colorectal cancer cell line model, we showed that ablation of AKAP4 lead to cell cycle arrest, cell death, inhibited migration, invasion and reduced tumor growth." (PMID 28881798, 2017). "Western blot of tumor lysate showed decreased expression of AKAP4, PKA and p-CREB in shRNA3 treated animals compared to NC shRNA animals." (PMID 28881798, 2017). "Taken together these observations support a strong relationship between the presence of a tumor in the lung and the detection of AKAP4 message in the peripheral blood samples." (PMID 26160834, 2015). "Another potential source of the AKAP4 signal are tumor derived exosomes which are released in large numbers and engulfed by tumor infiltrating lymphocytes including macrophages that are included in the PBMC fraction." (PMID 26160834, 2015). "It is noteworthy that AKAP4 knockdown markedly inhibited the tumor growth with reduced AKAP4 and PCNA expression." (PMID 26590805, 2015). "Follow-up studies in a small number of resected NSCLC patients revealed a decrease of AKAP4 expression post-surgical resection that remained low in patients in remission and increased with tumor recurrence." (PMID 26160834, 2015). "The tumor derivation of this signal is further supported by data demonstrating that the AKAP4 presence in PBMC RNA is significantly reduced after successful lung resection and that expression increases once again with a lung tumor recurrence." (PMID 26160834, 2015). "Results show that the AKAP-4 transcript was present in MM cell lines, primary MM cells, bone marrow, peripheral blood and spleens of tumor-bearing mice, but undetectable in tumor-free mice (healthy controls)." (PMID 21923911, 2011). "AKAP-4 is a cancer/testis antigen (CTA), a class of tumor associated antigens characterized by high expression in germ cells and cancer, strong immunogenicity and very low expression or absence in normal tissues." (PMID 21923911, 2011). "The results demonstrated the expression of both GFP and AKAP-4 and confirmed that the tumor masses originated from U266 cells." (PMID 21765917, 2011). "The specificity of this finding was confirmed by the failure to detect paraprotein- or AKAP-4- positive cells in tumor-free mice." (PMID 21923911, 2011). "Here we describe a new MM animal model in NOD-Rag1null IL2rgnull (NRG) mice that supports the engraftment of cell lines and primary MM cells that can be tracked with the tumor antigen, AKAP-4." (PMID 21923911, 2011). "Indirect ELISA was used to determine the concentration of human paraproteins (IgE and IgG) and AKAP-4 in the sera of tumor-bearing mice." (PMID 21923911, 2011). "After a six-week growth, the tumor volume and weight were significantly reduced in the siRNA #1 and siRNA #2 groups compared to the siNC group, respectively (**p < 0.01, vs. siNC), indicating a promising inhibitory effect by knocking down AKAP4." (PMID 35253625, 2022). "In addition, the biomarker of angiogenesis, VEGF, was dramatically downregulated in the siRNA #1 and siRNA #2 groups (**p < 0.01, vs. siNC), indicating that the in vivo angiogenesis in H460 tumor tissues was suppressed by the knockdown of AKAP4." (PMID 35253625, 2022).
tumor (continued). "Interestingly, we found that the killing ability of CTLs to tumor cell lines depended on the expression of AKAP4 and HLA-A*0201." (PMID 35967402, 2022). "In addition, the expression level of AKAP4 increased significantly with the development of neoplasm staging." (PMID 35253625, 2022). "Therefore, in the current study, we attempted to devise a multi-epitope-based vaccine via bioinformatics tools targeting the major tumor-associated antigens including SP17, AKAP4, and PTTG1, which have been implicated in in tumor proliferation and invasion." (PMID 35463817, 2022). "AKAP4 is a known cancer/testis gene located on the X chromosome and has been shown to be aberrantly expressed in a variety of different cancers as well as on circulating tumor cells (CTCs)." (PMID 26160834, 2015). "To determine if SP17/AKAP4/PTTG1 could trigger a tumor-specific cytotoxic response, we used CTA-loaded DCs to generate CTLs." (PMID 25739119, 2015). "Interestingly the tumour from patient 21, which harboured a FSIP2 amplification, also carried a missense mutation in AKAP4." (PMID 25609015, 2015). "Therefore, we next validated the various molecules by IHC in excised tumor sections of mice treated with AKAP4 shRNA3 or NC shRNA." (PMID 26590805, 2015). "Further, we investigated its role in cellular proliferation, migration, invasion, wound healing, colony forming abilities and tumor growth which suggested that AKAP4 could be used as a novel therapeutic target for CRC treatment." (PMID 26590805, 2015). "This makes AKAP-4 a very interesting target for PCa anti-tumor vaccination." (PMID 24834066, 2014). "Importantly, AKAP-4 was detectable in the sera of tumor-challenged mice and its levels increased over time, similarly to those of IgE and IgG." (PMID 21923911, 2011). "RT-PCR was performed to evaluate AKAP-4 mRNA expression in tumor-challenged or tumor-free mice." (PMID 21923911, 2011). "Additionally, we validated the use of AKAP-4 antigen to track tumor growth in vivo and to specifically identify MM cells in mouse tissues." (PMID 21923911, 2011). "Contemporaneously, AKAP-4, a member of scaffolding protein family, was used as a tumor marker." (PMID 21765917, 2011). "Thus, our in vivo findings supported our in vitro results indicating that AKAP4 may have role in tumor growth." (PMID 26590805, 2015). "Interestingly, high anti-AKAP4 antibody titers in the patient’s sera indicated high tumor burden." (PMID 23451156, 2013). "Additionally, we propose the use of AKAP4 as a universal biomarker to track tumor cells in vivo." (PMID 21923911, 2011). "Lastly, the growth of AKAP4-knockdown H460 cells in xenograft mice was investigated, along with the activity of the cAMP-PKA pathway and EMT progression in xenograft tumor tissues." (PMID 35253625, 2022). "The current study aimed to design a multi-epitope peptide vaccine targeting main cancer/testis antigens of SP17, AKAP4, and PTTG1, which have a major function in tumor cell proliferation invasion." (PMID 35463817, 2022). "We generated CTLs from 5 patients displaying SP17, AKAP4 and PTTG1 protein expression and demonstrated specific lysis of autologous tumor cells and CTA-expressing cell lines." (PMID 25739119, 2015). "In this study we evaluated RNA and protein expression patterns of SP17, AKAP4 and PTTG1 in NSCLC cell lines and primary tumor samples from NSCLC patients, compared to normal lung cells and tissues." (PMID 25739119, 2015). "For each antigen, we selected patients that tested positive for SP17, AKAP4, and PTTG1 protein expression in tumor cells." (PMID 25739119, 2015). "Western blot analysis revealed the down regulation of AKAP4 and PCNA protein in AKAP4 shRNA3 treated tumor lysates as compared to NC shRNA treated tumor lysates." (PMID 26590805, 2015). "Ablation of AKAP4 led to reduced cellular growth, migration, invasion and increased apoptosis and senescence of CRC cells in in vitro assays and tumor growth in human xenograft mouse." (PMID 26590805, 2015).